CD52 (CD52 molecule)
Diseases named in the same sentence as CD52 in open-access papers (continued):
Sharing a sentence is not in itself a finding about the gene and the disease.
follicular lymphoma (1 paper, 2021). Follicular lymphoma is a form of non-Hodgkin lymphoma characterized by a proliferation of B cells whose nodular structure of follicular architecture is preserved. "Building on UCART19′s initial success, Cellectis, Allogene and Servier begun investigating the use of TCR and CD52 KO CAR T cells in conjunction with an anti-CD52 recombinant antibody to treat relapsed or refractory large B cell lymphoma or follicular lymphoma." (PMID 34452392, 2021).
fungal infections (1 paper, 2020). "More recently, opportunistic bacterial, viral (including HBV reactivation), and fungal infections have become more prominent with the increasing use of T cell-depleting agents such as purine nucleoside analogs and the anti-CD52 monoclonal antibody alemtuzumab." (PMID 32393328, 2020).
Granuloma (1 paper, 2015). A compact, organized collection of mature mononuclear phagocytes, which may be but is not necessarily accompanied by accessory features such as necrosis. "CD52 expression was observed in lymphocytes surrounding granulomas, with larger numbers of lymphocytes in the TT, BT, and R1 granulomas, as well as lymphocytes infiltrating vessels, nerves, interstitial, arrector pili muscle, and epidermis." (PMID 26635870, 2015). "In BB, BL, LL, and R2 granulomas there were fewer CD52+ lymphocytes." (PMID 26635870, 2015).
Hodgkins lymphoma (1 paper, 2019). A heterogeneous group of malignant lymphoid neoplasms of B-cell origin characterized histologically by the presence of Hodgkin and Reed-Sternberg (HRS) cells in the vast majority of cases. "Immunomodulators aimed to achieve blocking of inhibitory molecules on the cell surface of immune effectors (i.e., Anti PD-1, anti-CD30, anti CD52, anti-CTLA-4, and anti-CD80), were approved for the treatment of patients with Hodgkin Lymphoma (HL)." (PMID 31357735, 2019).
hyperreactivity (1 paper, 2020). "Lastly, we show that a murine anti-CD52 antibody mimics the immune cell-depleting effects of a clinically used human anti-CD52 antibody and reduces allergen-induced airway hyperreactivity in mice." (PMID 32296059, 2020).
hypogammaglobulinemia (1 paper, 2021). "The depletion of anti-CD20 and anti-CD52 therapies was in fact linked to antibody deficiencies, and moreover, the extent of hypogammaglobulinemia induction correlated with a higher risk of infection." (PMID 34829815, 2021).
infertile (1 paper, 2024). "CD52 on sperm was shown to be the target of sperm-immobilizing antibodies in the serum of a minority of infertile women." (PMID 39737172, 2024). "The CD52 sialoglycan on sperm has been shown to be the antigenic target of circulating anti-sperm immobilizing antibodies, detected in a minor proportion of infertile women." (PMID 39737172, 2024).
Insulin resistance (1 paper, 2021). Increased resistance towards insulin, that is, diminished effectiveness of insulin in reducing blood glucose levels. "In addition, as previously reported, some genes beneficial to glucose tolerance were up-regulated in the group with low expression of CD52, suggesting that high expression of CD52 is associated with insulin resistance." (PMID 33705353, 2021).
lung adenocarcinoma (1 paper, 2021). A carcinoma that arises from the lung and is characterized by the presence of malignant glandular epithelial cells. "Upregulated CD52 is correlated with poor survival in patients with lung adenocarcinoma." (PMID 33986766, 2021).
lung carcinoma (1 paper, 2026). "Furthermore, 2 risk groups of patients with lung cancer, characterized by different prognoses and immune landscapes, were stratified using a risk scoring model that comprised 3 AS-related genes (CD52, FABP5, and FCGR3A)." (PMID 41731774, 2026).
lupus nephritis (1 paper, 2020). Glomerulonephritis in the context of systemic lupus erythematosus. "Lastly, patients presenting with lupus nephritis, or who had a history of lupus nephritis, had significantly lower levels of soluble CD52 in their plasma (p = 0.0015) suggesting differences in these patients’ regulation of CD52 expression." (PMID 33658999, 2020). "In support of this hypothesis, we observed significantly higher levels of soluble CD52 in patients without lupus nephritis compared to those with a history of lupus nephritis." (PMID 33658999, 2020).
metastatic cancer (1 paper, 2021). A carcinoma which has spread from the original site of growth to another anatomic site. "Besides CD52 and PTPRC that were highly expressed by metastatic cancer cells of both TNBC and non-TNBC." (PMID 34611125, 2021).
non-Hodgkin lymphoma (1 paper, 2022). Distinct from Hodgkin lymphoma both morphologically and biologically, non-Hodgkin lymphoma (NHL) is characterized by the absence of Reed-Sternberg cells, can occur at any age, and usually presents as a localized or generalized lymphadenopathy associated with fever and weight loss. "Since rituximab targeting CD20 was first approved for Non-Hodgkin’s lymphoma (NHL) in 1997, the US Food and Drug Administration (FDA) has approved a variety of therapeutic monoclonal antibodies, which can target CD19, HER-2, VEGFA, EGFR, and CD52, etc.." (PMID 36304470, 2022).
osteoarthritis (1 paper, 2022). A noninflammatory degenerative joint disease occurring chiefly in older persons, characterized by degeneration of the articular cartilage, hypertrophy of bone at the margins and changes in the synovial membrane. "In brief, we found four hub genes, i.e., CD4, SELL, ITGB2, and CD52 that are potential diagnostic biomarkers which may contribute to the diagnosis of osteoarthritis and provide further insight into the underlying molecular mechanisms for OA risk genes." (PMID 36468029, 2022). "Meanwhile, q-PCR results of clinical samples showed that four genes (CD4, SELL, ITGB2, and CD52) were upregulated in human primary synoviocytes compared with non-osteoarthritis samples." (PMID 36468029, 2022). "However, the role of CD52 in osteoarthritis is explored to a much lesser extent." (PMID 36468029, 2022).
ovarian tumor (1 paper, 2009). "We next tested the impact of anti-CD52 antibody therapy on ovarian tumor growth in vivo using the ID8-VEGF murine ovarian flank tumor model." (PMID 19545375, 2009). "Finally, anti-VLC therapy with an anti-CD52 immunotoxin significantly restricted ovarian tumor growth in a murine ovarian tumor model." (PMID 19545375, 2009). "Furthermore, CD52 expression was identified on the vast majority of ovarian tumor-associated Tie2+ monocytes, independent of their relationship to VLC, suggesting Alemtuzumab can target the majority of Tie2+ monocytes." (PMID 19545375, 2009). "Finally we assessed the impact of anti-CD52 immuno-toxin therapy on murine ovarian tumor growth." (PMID 19545375, 2009).
psoriasis (1 paper, 2024). An autoimmune condition characterized by red, well-delineated plaques with silvery scales that are usually on the extensor surfaces and scalp. "This analysis revealed the overexpression of SPRR2D, CD52, and PI3 in DCs isolated from psoriasis skin tissues." (PMID 38596682, 2024).
rheumatologic disorders (1 paper, 2025). "Alemtuzumab is an mAb targeting CD52, which has been used for relapsing–remitting multiple sclerosis, certain rheumatologic disorders, and hematologic malignancies." (PMID 41441522, 2025).
skin tumors (1 paper, 2024). "Little is known about the role of CD52 inhibitors in skin tumors." (PMID 39274345, 2024).
systemic AL amyloidosis (1 paper, 2016). "Furthermore, alemtuzumab, an anti‐CD52 antibody 28, or elotuzumab, a humanized monoclonal antibody against the surface antigen SLAMF7 29, may offer new treatment options in systemic AL amyloidosis for positive patients." (PMID 27109862, 2016).
systemic mastocytosis (1 paper, 2023). Systemic mastocytosis (SM) comprises a heterogeneous group of rare acquired and chronic hematological malignancies that are related to an abnormal proliferation of mast cells in tissue, including bone marrow, with or without skin involvement. "Notably, TMEM176B and CD52 were among the top 5 significant genes in all three datasets, with CD52 being reported as a marker of neoplastic MCs in patients with advanced systemic mastocytosis." (PMID 38031173, 2023).
tetanus (1 paper, 2024). A serious infectious disorder that follows wound contamination by the Gram-positive bacterium Clostridium tetani. "In the absence of seminal fluid, CF1D12 alone increased CD4+ T-cell proliferation in response to tetanus, which we attribute to blocking by CF1D12 of soluble CD52 released upon T-cell activation." (PMID 39737172, 2024).
vasculitis (1 paper, 2022). "Alemtuzumab, an anti-CD52 antibody, depletes lymphocytes for prolonged periods and, in retrospective studies, has induced sustained, treatment-free remissions in patients with refractory/relapsing vasculitis but has raised safety concerns of infection and secondary autoimmunity." (PMID 35365179, 2022).
tumor (68 papers, 2009 to 2026). "Here, we detected positive CD52 expression in tumors from TNBC patients and demonstrated that CD52 on TNBC cells facilitates immune evasion by engaging the inhibitory receptor sialic acid-binding Ig-like lectin G (Siglec-G) on tumor-associated macrophages." (PMID 41580422, 2026). "We further identified four top ranking up-regulated genes in peritoneal CLL cells from TCL1-Tg mice that are strongly associated with tumor progression, such as Cd52." (PMID 38469292, 2024). "We first evaluated the potency of anti-CD20 and anti-CD52 IgG subclass variants to kill different tumor cells in CDC assays." (PMID 39436656, 2024). "Based on the statistical comparison of gene copy numbers within the genomes of both cancer-prone and -resistant species, we identified novel gene targets linked to tumor predisposition, such as CD52, SAT1 and SUMO." (PMID 35741808, 2022). "Anti-CD52 immunotoxin therapy lead to a delay in the accumulation of tumor-associated ascites and an improvement in the median overall survival of treated animals." (PMID 19545375, 2009). "Administering anti-CD53 IgG1 could lead to even more significant loss of non-tumor cells than CD52-targeting alemtuzumab, which is typically reserved for salvage therapy in CLL due to widespread CD52 expression among non-B leukocytes." (PMID 25852576, 2015). "Ten female NOD-Prkdcem26 Cd52/Gpt mice were randomly divided into 2 groups to establish a xenograft tumor model." (PMID 40392374, 2025). "RASP-based reduced rank reconstruction of CD52 shows expression spreading into infiltrating immune cells located within the invasive tumor." (PMID 41370353, 2025). "Intriguingly, macrophage induction and tumor suppression are enhanced when PARPi and anti-CD52 are used in combination, indicating a novel combined pharmacotherapy." (PMID 40830526, 2025). "Consistently, the typical representative images of IHC staining showed that the number of CD52 positive cells in tumor tissues is significantly higher than that in normal tissues." (PMID 38817869, 2024). "Recently, it has been reported that CD52 is a prognostic biomarker related to the tumor microenvironment of breast cancer." (PMID 38817869, 2024). "The CD52 expression level was determined using IHC staining in tumor tissues (n=79) and matched normal tissues (n=88) samples from clinical NSCLC patients." (PMID 38817869, 2024). "Conversely, CD52 and KRT19 were identified as predictive biomarkers linked to the tumour microenvironment (TME) of BC,39, 42, 43 whereas genetic variations in IL7R dramatically raised the susceptibility to BC in Chinese Han women." (PMID 39098994, 2024). "Recently, Wang and co-authors identified CD52 as a key player in tumor immunity, affecting tumor behavior by regulating the associated tumor microenvironment." (PMID 35741808, 2022). "The coating of the magnetic nanoparticles consist of antibodies such as epithelial cell adhesion molecule (EpCAM) and CD52 as markers to attempt to remove tumor cells from the blood." (PMID 34067587, 2021). "Molecular targets for MS/SS are currently CD30, CCR4, CD25, CD52, and histone deacetylases, most of which are surface molecules specifically expressed on tumor cells." (PMID 34681738, 2021). "These epitope-switched CAR T cells retained cell killing competence against CD19+ tumor cells, and were resistant to alemtuzumab (anti-CD52) but sensitive to rituximab (anti-CD20) in complement-dependent cytotoxicity assays." (PMID 33526841, 2021). "The purpose of this study was to observe the effect of anti-CD52 mAb on transplanted tumor models of SCID mice." (PMID 34669957, 2021). "Treatment with Alemtuzumab, which recognizes CD52 on CAR T cells, would eliminate infused CD4 CAR T cells after tumor depletion, thus preventing toxicities associated with CD4+ cell aplasia caused by long-term persistence of CAR T cells." (PMID 33081391, 2020).
tumor (continued). "Daratumumab was also shown to induce CDC in cancer cells from MM patients, similar to alemtuzumab (CD52 mAb), which has been found to kill B cell tumor cells mainly via CDC." (PMID 31118070, 2019). "When we compared IL-2-activated CD52+ NK cells and CD52− NK cells, we found that CD52− NK cells exhibited 4-fold greater cytotoxicity against K562 tumor cells compared with CD52+ NK cells." (PMID 27560943, 2016). "ANT1034 also showed superior activity in a SCID mouse/human CD52 tumour xenograft model where a single 1 mg/Kg dose of ANT1034 led to increased mouse survival compared to a 10 mg/Kg dose of alemtuzumab." (PMID 26372145, 2015). "Animals were treated with anti-human CD52 antibodies on alternate days for seven doses starting 3 days after injection of tumour cells." (PMID 26372145, 2015). "Many in vitro maintained lymphoid-derived tumour cells have been shown to express CD52, however the level of expression can vary significantly and the stability of the expression is unpredictable." (PMID 26372145, 2015). "This is similar to the localization reported for Tie+ monocytes in other tumors Small CD52+/VE-Cadherin(-) cells, consistent with tumor infiltrating lymphocytes, were also observed." (PMID 19545375, 2009). "Twice-weekly intraperitoneal anti-CD52 therapy was initiated one week after the injection of tumor cells." (PMID 19545375, 2009). "CD52 expression is observed on numerous tumor infiltrating host cells including lymphocytes, neutrophils, and mast cells." (PMID 19545375, 2009). "FACS analysis of ficoll isolated tumor infiltrating host cells confirmed CD52 protein expression on greater than 90% of CD45+/VE-Cadherin+VLC (range 88–98%)." (PMID 19545375, 2009). "In order to test the effects of anti-CD52 antibody therapy on tumor growth in vivo, we developed an anti-CD52 immunotoxin." (PMID 19545375, 2009). "Additionally, cotreatment with anti-CD52 sensitized tumor cells to PD-1 blockade therapy in the spontaneous MMTV-PyMT TNBC model." (PMID 41580422, 2026). "Notably, CD8Teff cells emerged as a key determinant of immunotherapy efficacy and tumor classification as "hot" or "cold", and CD52 + DCs modulate CD8Teff cell activity by influencing antigen presentation." (PMID 40971094, 2025). "Furthermore, response patients demonstrated enhanced signaling in immune-regulating pathways, such as TNF and CXCL, indicating that CD52 + DCs play a key role in modulating immune responses and shaping the tumor microenvironment." (PMID 40971094, 2025). "Thus, CD52 + DC cells regulate CD8Teff activity by modulating antigen presentation and directly influencing cytokine activity, ultimately shaping the tumor microenvironment." (PMID 40971094, 2025). "Regarding trial target studies, anti-tumor immunity and cell primarily involves molecules associated with immune responses, including CD19 (4 trials, 8.5%), membrane-spanning 4-domains A1 (4 trials, 8.5%), and CD52 (3 trials, 6.4%)." (PMID 40777013, 2025). "In addition, CD52 expression was significantly correlated with tumor stage, T infiltration, tumor lymph node metastasis and distant tumor metastasis." (PMID 38817869, 2024). "Moreover, CD52 knockdown in mouse tumor tissues downregulated the expression of AKT pathway proteins and glycolytic-related proteins." (PMID 38817869, 2024). "The tumor burden of mice after CD52 knockdown was significantly reduced (p < 0.05)." (PMID 38817869, 2024). "Specifically, in two (P6, P7) of 10 primary samples, ibrutinib led to reduced viability of more than 50%, triggered considerable upregulation of surface CD52, and rendered the tumor cells more vulnerable to CD52 mAb mediated toxicity, as seen in the ibrutinib-sensitive cell line model." (PMID 36587029, 2022). "In this study, we identified that CD52 might play an important role in tumor immunity by regulating the TME of BC." (PMID 33240323, 2020).